ACTBP2 (ACTB pseudogene 2)
Gene: Processed pseudogene on chromosome 5 (77,784,881 to 77,786,003, forward strand). Ensembl gene ENSG00000213763.
Diseases named in the same sentence as ACTBP2 in open-access papers:
ACTBP2 is named in the same sentence as 2 diseases in open-access papers, as found by Europe PMC text mining. Sharing a sentence is not in itself a finding about the gene and the disease. The quoted sentences say what the papers report.
tumor (1 paper, 2022). "When profiling for microinstability an Egyptian study found a concordance between urine and tumor tissue samples regarding D16S476, D9S171, FGA, and ACTBP2 alterations (MSI and/or LOH), therefore, they evaluated it as a potential biomarker." (PMID 35955004, 2022).
ACTBP2 also shares sentences with these, for which no sentence is quoted: Obesity (1 paper).